CD226 (CD226 molecule)
Diseases named in the same sentence as CD226 in open-access papers (continued):
Sharing a sentence is not in itself a finding about the gene and the disease.
tumor (continued). "NEFM negatively correlated with PVR (CD155), an immune checkpoint on tumor cells and interacting with CD96, CD226, and TIGIT (T cell immune receptor with immunoglobulin and ITIM domains) on TILs to modulate immune function in tumor microenvironment." (PMID 34001208, 2021). "Co-inhibitory TIGIT and CD96 compete with co-stimulatory CD226 for their ligands CD155 and CD112 on dendritic cells (DCs) or tumor cells to suppress the anti-tumor immunity of TILs." (PMID 34858835, 2021). "CD226 promotes cytotoxicity and enhances anti-tumour responses, whereas TIGIT, which outcompetes CD226, negatively regulates anti-tumour responses." (PMID 33995362, 2021). "High expression of CD155 on tumor cells promotes dysfunctionality of tumor infiltrating CD8+ T cells by driving internalization and proteasomal degradation of the co-stimulatory receptor CD226 in CD8+ T cells in mouse and human tumors." (PMID 34367161, 2021). "TIGIT binds to its ligand PVR or CD155 on the tumour cells with a much higher affinity than its activating counterpart CD226 (DNAM-1), thereby inhibiting the interaction between CD226 and CD155 which is widely expressed on tumour cells." (PMID 33995362, 2021). "Signaling triggered upon CD155 binding to CD226 potentiates CD8+ T cell and NK cell cytotoxicity toward tumor cells." (PMID 32155826, 2020). "Engagement of CD155 with ligands including CD226 (DNAM-1) and CD96 has been demonstrated to drive anti-tumor immune responses, particularly those by NK cells." (PMID 32532329, 2020). "The current study discovered that TIGIT, CD226, and PD-1 were all involved in the MDS-mediated tumor immune response." (PMID 32903786, 2020). "TIGIT is expressed on both activated T and NK cells and interacts with two specific DNAM-1 (CD226) ligands, CD155 (PVR) and CD112 (nectin-2), which are expressed on both immune and tumor cells." (PMID 32610578, 2020). "An experiment in vivo has demonstrated that CD226 mediates phosphorylation of FOXO1 and activates NK cells through interaction with CD155-expressing tumor cells." (PMID 32850777, 2020). "Like NKG2D, CD226 and CD96 are receptors expressed on the surface of NK cells known to be important for tumour immune surveillance." (PMID 30908480, 2019). "Here, we discuss the interactions between PD-1, TIGIT, PVR, CD226, CD96 and CD112 and focus on how they work together to deliver immune stimulatory or inhibitory signals among tumor cells and immune cells within the TME." (PMID 29735917, 2018). "We have adopted this strategy and devised chimeric receptors where CD28-signaling domains were fused to the extracellular binding domains of either CD2, CD226 or TIGIT and thus can be engaged by CD58 or CD155 expressed on the tumor targets." (PMID 29707134, 2018). "Conversely, PVR (CD155), CD112 and CD226 (DNAM-1) are expressed by dendritic cells (DCs), T cells, tumor cells and many other cell types." (PMID 29735917, 2018). "TIGIT counterbalances CD226-mediated T-cell activation by competing with CD226 for binding to PVR, a receptor that is expressed in multiple tumor types." (PMID 30400822, 2018). "Both are also ligands to DNAX accessory molecule-1 (DNAM-1, CD226), which has immune activating properties for NK cells and T cells, promoting tumor cell lysis." (PMID 29855615, 2018). "CD155, which serves as a ligand for CD226 and CD96 receptors is also overexpressed in tumor cell lines and primary tumors and promotes their invasion and migration." (PMID 21637820, 2011). "As a cellular membrane triggering receptor, CD226 is involved in the NK cell- or CTL-mediated lysis of tumor cells of different origin, including freshly isolated tumor cells and tumor cell lines." (PMID 19490613, 2009). "The specific interaction between CD226 (on NK cells) and CD155 or CD112 (on tumor cells) plays an important role in the NK-mediated lysis of tumor cells." (PMID 19490613, 2009).
tumor (continued). "DNAM-1 (CD226) is a critical activating receptor on the surface of NK cells that mediates their activation by recognizing ligands such as Nectin-2 (CD112) and PVR (CD155), which are expressed on the surface of tumor cells." (PMID 40463500, 2025). "TIGIT, DNAM-1 (CD226), CD96, and CD112R are expressed on T cells and natural killer (NK) cells, while their ligands—CD155, CD112, CD113, and CD111—are expressed on APCs or tumor cells." (PMID 40356928, 2025). "Our results align with previous findings from the previous mouse model, where the frequency of TIGIT+ CD8+ T cells was positively correlated with tumor burden, while the frequency of CD226+ CD8+ T cells showed a negative correlation." (PMID 39531203, 2025). "PVR/TIGIT, NECTIN2/CD226, and FAM3C/PDCD1 were relatively more strongly expressed in Plac1+ epi‐CD4+ T cells than Plac1− epi‐CD4+ T cells and PVR was specific for Plac1+ tumor cells, which was subsequently validated in HNSCC cells in vitro and in the TMA cohort by mIF." (PMID 40056047, 2025). "Additionally, γδT cells express DNAM-1 (CD226), which binds to CD155 (PVR) and CD112 (Nectin-2), further strengthening tumor recognition and immune activation." (PMID 40226616, 2025). "Given the significant immunostimulatory role of CD226 via VAV1, agonistic CD226-targeting mAbs could potentially serve as promising anti-tumour regimen." (PMID 38440738, 2024). "Another study reported the non-redundant role of CD226 costimulation in conventional CD8 + T cells interacting with non-professional APCs such as tumor cells but not DCs57." (PMID 39349829, 2024). "Moreover, we also identified BTN3A3, a surface molecule contributing to the recognition of phosphoantigens and DNAM-1 (CD226), an activating receptor recognizing CD155 and CD112 that are often upregulated on tumour cells." (PMID 39451262, 2024). "However, recent studies have revealed a positive correlation between the expression of CD226 or CD2-CD58 and clinical outcomes across various tumor types in response to cancer treatment, including ICIs and chimeric antigen receptor (CAR) T-cell therapies." (PMID 39349829, 2024). "Many recent reports, especially in the field of tumor immunology, have investigated the expression of the immune checkpoint molecules TIGIT, CD226 and CD155 and their possible role in immune regulation, while fewer papers have been published in the context of pregnancy." (PMID 38326745, 2024). "Both TIGIT and CD96 inhibit NK and T cell function via binding to CD226, indicating a possibility that ITGAL may suppress NK and CD8+ T cell’s killing activities of tumor cells." (PMID 37835514, 2023). "CD226 can compete with the inhibitory receptors CD96 and T cell immunoreceptor with Ig and ITIM domain (TIGIT) expressed on T cells for binding to CD155 overexpressed in tumor cells to exert anti-tumor effect." (PMID 37312116, 2023). "We found moderate positive correlation between the frequency of CD155 expression on mAPC populations and TIGIT and CD96 expression on T and NK cell subsets within the tumours, but not with CD226 or PD-1." (PMID 37596248, 2023). "CD226 (also known as DNAM-1) and CD112 (nectin-2) are also cell surface receptors that are expressed on various immune cells, including T cells, NK cells, and DCs, as well as on many tumor cells." (PMID 37345057, 2023). "Moreover, CD226 seems to correlate better with strong immune activation in liver metastasis than in primary CRC, despite the known immunosuppressive tumor microenvironment (TME) in the liver and the inflammatory context in primary CRC." (PMID 36717657, 2023). "As a result, the expression of co-stimulatory receptors CD226 and co-inhibitory receptors TIGIT and CD96 on NK cells suggest that CD155 may play a dual role in tumor immunity." (PMID 36674817, 2023). "Moreover, the blockade of TIGIT and PD-1 can help restore the CD226 signaling on CD8+TILs and optimize the CD8+T cell-mediated anti-tumor response." (PMID 37056782, 2023).
tumor (continued). "Because CD226 expression was dampened in liver metastases, in contrast to that in PBMCs of CRC patients, we hypothesized that tumor-derived immunosuppressive cytokines contribute to CD226 downregulation." (PMID 36717657, 2023). "CD155 combines with CD226 to enhance T/NK cell-mediated cytotoxicity and promote anti-tumor immune response, but also interacts with TIGIT and CD96 to induce tumor immune escape and promote tumor progression." (PMID 37441080, 2023). "CD8+CD226+IFN-γ+T cell population might develop a high TIGIT expression pattern, resulting in decreased CD8+T cell- or NK cell-mediated tumor reactivity." (PMID 37056782, 2023). "Moreover, natural cytotoxicity receptors (NCRs), i.e., NKp30, NKp44, NKp46, and DNAM-1 (CD226), can also be expressed on polyclonal γδ T cells and contribute to tumor cell recognition and killing." (PMID 36831606, 2023). "Within the subset of tumours where TIGIT-expressing cells do not commonly co-express CD226, this will likely be the dominant mechanism of action." (PMID 37596248, 2023). "The CD226-TIGIT-CD96 axis is involved in T cell and NK cell anti-tumor responses and may represent an attractive target for immunotherapy." (PMID 36140247, 2022). "These three modules contained recognized immune-related genes, such as CD86 and CD226, which have been reported to increase the downstream activation of NF-κB and CXCL9 whose secretion recruited CD8+ T cells into the tumor bed." (PMID 35237300, 2022). "Given the expression pattern of CD226 and CD28 on CD8+ T cell subsets that likely contribute to a robust response against tumors, optimal activation of the full repertoire of tumor-reactive CD8+ T cells is thus likely to require the coordinate inhibition of both TIGIT and PD-1." (PMID 35263569, 2022). "We previously observed that the anti-tumor efficacy of combined anti-PD-L1 and anti-TIGIT blockade in mice is abrogated by a CD226-blocking mAb, suggesting that costimulation by both CD226 and CD28 is required to overcome inhibition by PD-1 and TIGIT." (PMID 35263569, 2022). "This may be important in the context of TILs expressing varying levels of CD28, CD226, PD-1, and TIGIT, and myeloid or tumor cells expressing PD-L1 and PVR." (PMID 35263569, 2022). "Although PD-1 and TIGIT are thought to regulate different costimulatory receptors (CD28 and CD226), effectiveness of PD-1 or TIGIT inhibition in preclinical tumor models was reduced in the absence of CD226." (PMID 35263569, 2022). "Regardless of mechanism, the reduction of CD226 on immune cells in tumor-bearing hosts and prevalence of other axis members, raises several questions." (PMID 35812451, 2022). "In addition to recognizing tumor surface antigens through CARs, CAR-NK cells recognize tumor cells through various receptors such as natural cytotoxic receptors NKp46, NKp44, NKp30, NKG2D, and DNAM-1 (CD226)." (PMID 36741400, 2022). "Similarly, we found that in KPC4580P tumor bearing mice, the majority (80%) of the TIGIT+ cells also express PD-1 but low levels of CD226." (PMID 36569934, 2022). "Furthermore, mice with a Y319F mutation in CD226, which abrogates recruitment of the E3 ubiquitin ligase CBL-B for ubiquitinylation and proteasomal degradation, exhibited increased CD226 expression on CD8+ T cells and suppressed tumor growth." (PMID 35874734, 2022). "CD226 recognizes the Nectin-family ligands CD155 and CD112 on tumor cells." (PMID 33546248, 2021). "Specifically, we hypothesized that by inhibiting BCL9 activity, we could shift the balance of CD226 and CD96 checkpoints towards more cytotoxicity and thereby impede tumor growth." (PMID 34417435, 2021). "Unfortunately, CD226 expression is down-regulated on CD8+ TILs in mouse and human tumors, especially on CD8+PD-1hi exhausted dysfunctional CD8+ TILs which have been shown to contain the majority of tumor-reactive cells." (PMID 34367161, 2021).
tumor (continued). "Blockage of CD226 completely abrogated the effect of TIGIT/PD-L1 in the tumor but did not impact IFN-γ-producing CD8+ T cell frequency in the tumor-draining lymph node, suggesting a unique interplay among CD226, TIGIT and PD-1 in the tumor microenvironment." (PMID 34417435, 2021). "Both ligands are expressed on antigen presenting cells (APCs) and many non-hematopoietic cell types, including tumor cells, and share a signaling network with the costimulatory receptor CD226 (DNAM-1)." (PMID 33629951, 2021). "CD155 is another immune checkpoint protein, expressing on tumor cells and interacts with CD96, CD226, and T cell immunoreceptor with immunoglobulin and ITIM domains (TIGIT) on tumor-infiltrating lymphocytes to modulate the immune function in tumor immune microenvironment." (PMID 32411795, 2020). "The ligands for the CD226 and CD96 receptors on the tumour cell are CD112 and CD155." (PMID 30908480, 2019). "In comparison with matched ESCC patient blood samples, lower percentages of activator receptors, such as NKp30, CD16, NKp46, NKG2D, and CD226, and higher percentages of inhibitory receptors, such as NKG2A, were observed in adjacent tissues and tumour tissues (p < 0.05)." (PMID 31324197, 2019). "The regulation of CD96 on the NK cell is, unlike CD226, independent of the suppressive effects of the tumour cell alone." (PMID 30908480, 2019). "Furthermore, we observed that platelet cloaked tumour cells have significantly decreased expression of the CD112 and CD155 ligands that activate CD226/CD96." (PMID 30908480, 2019). "Given the role of platelets in regulating tumour cell expressed ligands and NK cell expressed receptors in the NKG2D-MICA/MICB system, we hypothesised that the CD226/CD96-CD112/CD155 axis would be regulated in a similar manner." (PMID 30908480, 2019). "First of all, CAR NK cells may conjugate the killing activity based on CAR-specific mechanisms with their spontaneous tumor cytotoxic capability, mediated by receptors such as NKp46, NKp44, NKp30, NKG2D, and DNAM-1 (CD226)." (PMID 31212634, 2019). "A similar effect was observed for CD96 with significantly decreased expression in response to platelet cloaked tumour cells, platelets and releasate suggesting a role for both in CD96 suppression, suggesting that CD226 and its CD96 co-receptor are suppressed in concert." (PMID 30908480, 2019). "Additionally, we describe the novel mechanism of platelets and their soluble molecules downregulating the receptors and ligands of the CD226/CD96-CD155/CD112 axis, further inhibiting NK cell functions and promoting tumour cell survival." (PMID 30908480, 2019). "From an immunological point of view, interactions between nectins and immune modulatory receptors such as DNAM-1 (CD226) and TIGIT are of particular interest due to their involvement in regulation of effector cell function and their recently appreciated role in anti-tumor responses." (PMID 31231358, 2019). "The findings therefore indicate that CD226 and CD96 could contribute to NK cell dysfunction and thereby induce PC progression and tumor immune escape." (PMID 27626490, 2016). "PVR recognition by CD226 potentiates CD8 T cell and NK cell cytotoxicity toward tumor cells." (PMID 26347741, 2015). "However TIGIT inhibition of T cells seems mediated by CD226 disruption as CD226 blockade annihilates the curative impact of TIGIT and PD-L1 co-blockade on both tumor growth and chronic infection." (PMID 26347741, 2015). "Additionally, the up-regulation of CD5, CD24, CD70, CD226 and PDCD1 (PD-1) that usually express on the surface of T cells, B cells, dendritic cells, NK cells, and tumor cells have also been observed." (PMID 23191987, 2012). "Such CAR-independent cytotoxicity, however, may likely be due to endogenously expressed NKG2D and other activating receptors, particularly DNAM-1 (CD226), which has been described to mediate strong TCR-independent lysis of many tumor cell lines." (PMID 22355347, 2012).
tumor (continued). "In addition, these cells also share other receptors with innate NK cells such as FcγRIIIa (CD16) which is required to recognize opsonized tumor cells, DNAX accessory molecule (DNAM-1, CD226) and natural cytotoxicity receptors (NCRs) NKp46, NKp44 and NKp30 which promote anti-tumor cytotoxicity." (PMID 38426099, 2024). "CD226, also known as DNAM1 (DNAX accessory molecule-1), is broadly expressed on T cells, natural killer (NK) cells, platelets, monocytes, and a subset of B cells, and it is also identified as a crucial co-activating receptor to restrain CD8+T-mediated anti-tumor response." (PMID 37056782, 2023). "Blockade of CD226 with anti-CD226 antagonist mAb did not influence the tumor growth in mice." (PMID 33670993, 2021). "Our results suggest that a lower percentage of CD226+ and CD96+ NK cells may contribute to tumor immune escape in PC patients; moreover, the use of NK cells with high CD226 and CD96 expression to treat PC cells with high CD155 expression may have potential and should be explored in the future." (PMID 27626490, 2016). "CD226-Fc fusion protein can notably inhibit the cytotoxicity of normal PBMC against K562 cells, indicating that the increased sCD226 might be one of the immune escape strategies used by tumor cells." (PMID 19490613, 2009). "Although soluble CD155 has been detected in human serum and cerebrospinal fluid and is anticipated to be one of the mechanisms of tumor immune escape, there has been no report on soluble CD226 (sCD226) or the levels of membrane CD226 (mCD226) and their relationship in tumors." (PMID 19490613, 2009). "Therefore, an accurate assessment of the intra-tumor T cell expression of TIGIT along with that of CD226, which directly competes for the binding to CD155, is critically required at the single patient level to fully take advantage from PARPi-mediated increase in CD155 expression on tumor cells." (PMID 36428727, 2022). "Recognition of induced self on tumor cells triggers a number of non-MHC class I–restricted activating receptors, such as NK group 2D (NKG2D), DNAX accessory molecule-1 (DNAM-1/CD226), and the natural cytotoxicity receptors (NCRs)." (PMID 30708970, 2019). "Recognition of abnormal self on tumor cells triggers a number of non-MHC class I-restricted activating receptors, such as NK group 2D (NKG2D), DNAX accessory molecule-1 (CD226), and the natural cytotoxicity receptors." (PMID 29765374, 2018). "However, high CD226 expression levels on CD4+ and CD8+ T cells did not correlate with CD3+ density in or around the tumor." (PMID 36717657, 2023). "TIGIT competes with the immunoactivator receptor CD226 (DNAM-1) for the same ligands: CD155 (poliovirus receptor, PVR) and CD112 (Nectin-2 or PVRL2), expressed on APCs, T cells and some non-hematopoietic cell types like tumor cells." (PMID 34335585, 2021).